IL6 (interleukin 6)
Diseases named in the same sentence as IL6 in open-access papers (continued):
Sharing a sentence is not in itself a finding about the gene and the disease.
macular edema (46 papers, 2007 to 2025). "Elevated levels of VEGF and inflammatory markers, such as interleukin-6, are closely associated with macular edema severity and treatment response." (PMID 39857689, 2025). "Serum amyloid A as a major protein involved in the acute and chronic stages of inflammation, and IL-6 and bFGF were significantly associated with the extent of macular edema in patients with RVO." (PMID 23861862, 2013). "Intraocular concentrations of IL-6 and IL-8 (particularly IL-6) are significantly associated with the volume of macular edema in patients with CNV." (PMID 22419849, 2012). "IL-6 was shown to be associated with the volume of macular edema in patients with CNV." (PMID 38007487, 2023). "IL-6 is significantly associated with the volume of macular edema in patients with CNV." (PMID 38007487, 2023). "Thus, the inflammatory cytokine IL-6 can cause endothelial barrier dysfunction and increase endothelial permeability, leading to macular edema." (PMID 23675018, 2007). "IL6 plays a crucial role in retinal inflammation and macular edema by inducing VEGF production and facilitating vascular leakage through the downregulation of tight junction proteins in retinal endothelial cells." (PMID 40455044, 2025). "Antibodies targeting interleukin 6 (IL-6) are currently being evaluated in clinical trials for the treatment of uveitic macular edema and are discussed for their therapeutic potential in macular edema due to retinal neovascular disease." (PMID 38190125, 2024). "Correlation analysis demonstrated that IL-8 was significantly correlated with increasing macular edema, and both IL-8 and IL-6 were the only cytokines to show positive correlations with higher cytokine levels and increased CST (i.e., poorer outcome)." (PMID 39325472, 2024). "IL-6 inhibitors have also demonstrated their use in treating treatment-refractory macular edema due to post-operative complications or retinal insults." (PMID 36902105, 2023). "There is abundant experimental data that supports the vital role of IL-6 in the molecular pathophysiology of macular edema from a variety of etiologies." (PMID 36902105, 2023). "The utility of IL-6 inhibitors for macular edema secondary to NIU has been studied for various forms of NIU." (PMID 36902105, 2023). "She developed macular edema following cataract surgery and responded extremely well to the inhibition of IL-6." (PMID 37205347, 2023). "Papers that elucidated the molecular pathophysiology of IL-6 in the genesis of macular edema were included." (PMID 36902105, 2023). "And the levels of VEGF and IL-6 in aqueous humor are significantly correlated with macular edema severity in diabetic patients." (PMID 38034528, 2023). "Clinical trials of biologic drugs that target IL-6 signaling – such as tocilizumab and sarilumab – for macular edema are ongoing, with initial positive results." (PMID 36960343, 2023). "In particular, IL-6 inhibitors have been reserved for use in treatment-resistant macular edema unresponsive to traditional therapies such as steroids, tumor necrosis factor alpha (TNF-alpha) inhibitors, or anti-VEGF inhibitors." (PMID 36902105, 2023). "In diabetic patients, the aqueous levels of vascular endothelial growth factor (VEGF) and interleukin-6 (IL-6) are significantly correlated with the severity of macular edema, as well as with aqueous flare intensity." (PMID 36357454, 2022). "The levels of HIF-1α mRNA, miR-210, MCP-1, VEGF and IL-6 in the aqueous humor of the CRVO combined with macular edema group were higher than those of the cataract control group (P < 0.05)." (PMID 35799735, 2022). "IL-6 is reportedly one of the most measurable inflammatory cytokines in macular edema and thus has predictive value in anti-VEGF treatment." (PMID 36761168, 2022). "Compared with the cataract control group, MCP-1, VEGF and IL-6 levels in the aqueous humor of the CRVO combined with macular edema group were higher (P < 0.05).Table-III." (PMID 35799735, 2022).
macular edema (continued). "This is consistent with the key role of TNF-alpha in the regulation of ocular levels of different chemokines, including VEGF, TGF-beta, angiotensin II, IL-1, IL-6, and IL-8, which drive the development of macular edema and choroidal neovascularization." (PMID 32069898, 2020). "Vitreous fluid levels of VEGF, sICAM-1, and IL-6 were also significantly correlated with the severity of macular edema in the CRVO group (ρ = 0.49, P = 0.029, ρ = 0.66, P = 0.003, and ρ = 0.61, P = 0.006, respectively)." (PMID 24325604, 2013). "Triamcinolone has also been linked to reductions in other inflammatory cytokines, such as IL6, ICAM-1, MCP-1, and PDEF, which have all been implicated in the pathogenesis of macular oedema." (PMID 24527231, 2012). "After the completion of pre-treatment of PRP, macular edema defined as increase of foveal thickness was prominently worsened, and the vitreous level of IL-6 in PRP pre-treated group showed statistically higher than that in control." (PMID 23675018, 2007). "Patients with macular edema and some severe retinal diseases have been shown to have high IL-6 levels, so the present results suggest that cell counts on WOCT might be involved with the severity of pathology." (PMID 38232093, 2024). "Indeed, IL-6 has proangiogenic properties, the intraocular concentration of this cytokine being more closely correlated to the occurrence of macular edema than VEGF-A." (PMID 37408242, 2023). "Circumstantial evidence implicates IL-6 in diseases leading to macular edema." (PMID 36960343, 2023). "The role of IL-6 in the development of macular edema has been well elucidated." (PMID 36902105, 2023). "IL-6 is a key cytokine in retinal inflammation and macular edema." (PMID 36902105, 2023). "In BRVO, IL-6 is significantly related to NPA and caused macular edema secondary to BRVO." (PMID 35783660, 2022). "The inflammatory cytokines, TNF-α and IL-6, are strongly implicated in the development of non-infectious retinal inflammation and the macular oedema that often accompanies this." (PMID 35208767, 2022). "In addition, to clarify which factor (VEGF, sICAM1, or IL6) was most closely correlated with the severity of macular edema, multiple linear regression analysis with stepwise selection of variables was performed." (PMID 24325604, 2013). "There was also a significant correlation between the aqueous flare value and the severity of macular edema in CRVO, and vitreous fluid levels of VEGF, sICAM-1, and IL-6 were significantly correlated with both the aqueous flare value and the severity of macular edema in our CRVO patients." (PMID 24325604, 2013). "In addition, VEGF plays an important role in the destruction of BRB and the onset of macular edema, while IL-6 may contribute to outer BRB dysfunction." (PMID 41163032, 2025). "By W12, there was a strong positive correlation between IL-8 (r = 0.55, P = 0.024) and IL-6 (r = 0.45, P = 0.057) with increasing CST, indicating that higher levels of IL-8 or IL-6 cytokines correlate with increasing macular edema." (PMID 39325472, 2024). "As a pro-inflammatory factor, Interleukin-6 was up-regulated in RVO, especially in CRVO but decreased in macular edema secondary to RVO." (PMID 35783660, 2022). "The aqueous flare value is also significantly correlated with the severity of macular edema, as well as vitreous levels of VEGF and IL-6, in patients with retinal vein occlusion." (PMID 36357454, 2022). "The aqueous humor levels of IL-1β, IL-6, IL-8, MCP-1, IP-10, and VEGF increased with increasing severity of macular edema." (PMID 25923230, 2015). "The present study showed that aqueous levels of IL-1β, IL-6, IL-8, IP-10, MCP-1, and VEGF were increased in patients with postcataract surgery macular edema and were positively correlated with FCPT 4 weeks following cataract surgery in diabetic patients." (PMID 25811020, 2015).
macular edema (continued). "There was also significant correlation between the severity of macular edema and the vitreous fluid levels of VEGF, sICAM-1, and IL-6 in our CRVO patients." (PMID 24325604, 2013). "Accordingly, we investigated the relation between macular edema and inflammatory parameters (flare value and vitreous fluid levels of VEGF, sICAM-1, and IL-6) in patients with CRVO." (PMID 24325604, 2013). "The role of IL-6 in inflammation in DME and macular edema due to RVO has already been reported in several studies." (PMID 23861862, 2013). "Intravitreal levels of VEGF and IL-6 correlate with the severity of macular edema and the size of the non-perfusion area." (PMID 36960343, 2023). "The use of IL-6 inhibitors in macular edema secondary to non-uveitic processes has only begun to be explored." (PMID 36902105, 2023). "It is thus not surprising that the use of IL-6 inhibitors in treatment-resistant macular edema in the setting of non-infectious uveitis has been well documented as an effective treatment option." (PMID 36902105, 2023). "In the CRVO combined with macular edema group, HIF-1α mRNA and miR-210 levels in the aqueous humor were positively correlated (r = 0.522, P < 0.05), and they were positively correlated with MCP-1, VEGF and IL-6 levels (P < 0.05)." (PMID 35799735, 2022). "Meanwhile, IL-6 stimulates NF-κB and VEGF, which are directly relevant to macular edema." (PMID 35783660, 2022). "In macular edema secondary to BRVO, VEGF cooperates with ICAM-1, IL-6, and MCP-1 to impair the BRB." (PMID 35783660, 2022). "Since JAK1 is also involved in the signal transduction of other barrier-damaging cytokines, such as IL-6 and VEGF, targeting this pathway may be a novel approach for the management of macular oedema, particularly those who are resistant to anti-VEGF therapy." (PMID 34356895, 2021). "Mean levels of VEGF and IL6 were increased in these eyes and correlated with the extent of retinal nonperfusion and the severity of macular edema." (PMID 28044102, 2016). "Inflammation may induce an increase of vascular permeability and disrupt the blood-aqueous barrier via release of inflammatory factors (VEGF, IL-6, MCP-1, and sICAM-1) in BRVO patients with macular edema." (PMID 24884703, 2014). "We also found that vitreous fluid levels of VEGF, IL-6, and MCP-1 were significantly correlated with the aqueous flare value and the severity of macular edema in the BRVO patients, indicating that inflammatory cytokines are elevated in patients with higher flare values." (PMID 24884703, 2014). "We investigated the relations between the aqueous flare value and vitreous levels of vascular endothelial growth factor (VEGF), soluble intercellular adhesion molecule-1 (sICAM-1), and interleukin-6 (IL-6) in patients with CRVO and macular edema or patients with idiopathic macular hole (MH)." (PMID 24325604, 2013). "Tocilizumab demonstrated notable efficacy in reducing macular edema and optic disc swelling in this patient, although without accompanying visual improvement, indicating that IL-6 may play a critical role in the pathophysiology of the condition." (PMID 41269507, 2025). "Pearson’s correlation analysis showed that in the CRVO combined with macular edema group, HIF-1α mRNA and miR-210 levels in the aqueous humor were positively correlated (r = 0.522, P < 0.05), and they were both positively correlated with MCP-1, VEGF and IL-6 levels (P < 0.05) (Table-IV)." (PMID 35799735, 2022). "Indeed, IL-6 signaling blockade suppresses EAU, and it has been recently described that IL-6 reversibly disrupts the integrity of the blood-retinal barrier in vitro, a key feature of the pathophysiology of macular edema." (PMID 33101305, 2020).
macular edema (continued). "A previous study measured the concentrations of VEGF and IL-6 in aqueous humor in diabetic patients with or without macular edema by enzyme linked immunosorbent assay (ELISA) and demonstrated that high VEGF and IL-6 levels in the aqueous humor are involved in the pathogenesis of macular edema." (PMID 25923230, 2015). "Therefore, the correlation between the aqueous flare value and the severity of macular edema in the CRVO group points to a role of inflammatory factors (VEGF, sICAM-1, and IL-6) in the development of macular edema by increasing vascular permeability and/or diapedesis of leucocytes." (PMID 24325604, 2013). "Therefore, the correlation between aqueous flare and foveal thickness in this group might suggest that these inflammatory factors (VEGF, IL-6, MCP-1, and sICAM-1) are involved in the development of macular edema by increasing vascular permeability and/or promoting diapedesis of leukocytes." (PMID 24884703, 2014). "In conclusion, PRP influenced vitreous level of IL-6 but not VEGF, leading to macular edema, which suggests that IL-6 plays critical roles of PRP induced macular edema." (PMID 23675018, 2007). "This study showed that intraocular IL-6, IL-8, IL-1β, TGF-β, bFGF, SAA, and VEGF were strikingly higher in patients with macular edema than in the control patients, regardless of whether this was due to CRVO or BRVO." (PMID 23861862, 2013).
Sjögren’s syndrome (46 papers, 2006 to 2025). "Increased activity of Th1 and Th17 cells has been demonstrated in both OCP and Sjögren’s syndrome, accompanied by elevated levels of IL-1β, IL-6, IL-17, TNF-α, and IFN-γ in periocular tissues." (PMID 41373875, 2025). "In summary, elevated salivary IL-6 levels in patients with Sjögren’s syndrome reflect active local inflammation of the salivary glands, promote B-cell maturation and autoantibody production, and are associated with greater clinical severity." (PMID 41301757, 2025). "This study aims to establish and evaluate a risk prediction model for coronary heart disease (CHD) in patients with primary Sjögren’s syndrome (pSS) based on peripheral blood levels of interleukin-6 (IL-6) and the percentage of regulatory T cells (Treg%)." (PMID 39664378, 2024). "Drugs such as infliximab (TNF family), etanercept (TNF family), tocilizumab (IL-6), and anakinra (IL-1), have also been evaluated as cytokine-targeted therapies in Sjögren’s Syndrome." (PMID 37232794, 2023). "S1P triggers Ca2+ signaling and induces the expression of interleukin 6 (IL-6) and Fas, which are known to be involved in a Sjögren’s syndrome-related apoptotic pathway." (PMID 36982432, 2023). "Elevated levels of salivary IL-6 have been shown to correlate significantly with the degree of lymphocytic infiltration in the labial salivary glands of patients with Sjögren’s syndrome." (PMID 36300113, 2022). "We reported that the production of BAFF (B cell-activating factor) and IL-6, both of which are involved in survival and differentiation of B cells, is dysregulated in monocytes of patients with primary Sjögren’s syndrome (pSS)." (PMID 32576236, 2020). "A similar induction of IL-6 by BAFF was also recently reported in monocytes of patients with primary Sjögren syndrome." (PMID 24289101, 2013). "IL-6 plays a role in the pathogenesis of Sjögren’s syndrome." (PMID 41301757, 2025). "Salivary cytokines have been investigated in patients with xerostomia as a secondary condition to Sjögren’s syndrome, with the observation of an increase in salivary interleukin-6 (IL-6) in such individuals—though few studies have been conducted on xerostomia due to other causes." (PMID 34884343, 2021). "Notably, Sjøgren’s Syndrome (SS) has been associated with overexpression of proinflammatory cytokines, including TNF-α, IL-7, IL-1β, IL-6, IL-10, IL-17, IL-18 and gamma-interferon (γ-IFN)." (PMID 29997338, 2018). "Similarly to the entire patient group, higher IL-6 and adiponectin serum levels were noted in patients with Sjögren's syndrome as compared to healthy controls (P = .05 and P = .04, resp)." (PMID 21234350, 2010). "In Sjögren syndrome, the ocular surface epithelium is a target of the autoimmune process, and increased levels of IL6 could be referred to as the direct involvement of the conjunctiva in the pathogenic mechanism of the disease, indicating a relevant role in ocular surface inflammatory damage." (PMID 26221061, 2015). "Tear proteomics has already identified cytokines and proteases—including IL-17, IL-6, TNF-α, and MMP-9—that correlate with disease severity in OCP, TAO, and Sjögren’s syndrome." (PMID 41373875, 2025). "Molecular profiling of tears has revealed elevated levels of IL-6, IL-17, TNF-α, and matrix metalloproteinase-9 (MMP-9) in patients with OCP, TAO, and Sjögren’s syndrome, correlating with disease severity." (PMID 41373875, 2025). "Some of the pro-inflammatory cytokines thought to play an important role in Sjogren’s syndrome pathophysiology are the interferons (IFN), IL-12, IL-18, TNF-α, IL-1β, IL-6 and B-cell activating factor (BAFF)." (PMID 36147586, 2022). "The study aimed to quantify certain cytokines involved in the pathomechanism of primary Sjögren syndrome (IL2, IL5, IL6, IL10, IL13, TNFα, IFNγ) and determine their common clinical correlation." (PMID 36143051, 2022).
Sjögren’s syndrome (continued). "One study involved 58 patients with primary Sjögren's syndrome (pSS) with elevated levels of YKL-40, IL-6, and TNF-α." (PMID 36248435, 2022). "Research into more clinical indications is ongoing, including IL-6 driven diseases: large-vessel vasculitis, type I IFN-related diseases: monogenic interferonopathies, scleroderma, myositis, and primary Sjogren’s syndrome." (PMID 34824210, 2021). "Decreased expressions of IL-6, IL-10, and IFN-γ were also observed for purified protein derivative-stimulated PBMC in patients with Sjogren’s syndrome with myalgia." (PMID 23245186, 2012). "In Sjögren's syndrome there are increased levels of inflammatory mediators (PGE2, thromboxane B2, IL-2 and IL-6) in saliva, which can assist in the diagnosis." (PMID 18221457, 2008). "Furthermore, interleukin levels such as IL-1a, IL-1b, IL-6, IL-8, TNF-a, and MMP-9 have been detected in Sjogren’s syndrome patients." (PMID 39408709, 2024). "Pro-inflammatory cytokines IL-1β, IL-6, IL-17 and TNF-α, as well as chemokines CXCL8, CXCL10, and CXCL13 are significantly elevated in the saliva of patients with Sjögren’s syndrome compared to healthy controls, and that their levels are correlated with the activity and severity of disease." (PMID 38714918, 2024). "TLR2, TLR3, and TLR4 were strongly expressed on the SGECs of patients with Sjögren syndrome, and TLR2 signaling induces the production of IL-23/IL-17 via IL-6 and signal transducer and activator of transcription (STAT) in the NF-κB pathway in Sjögren syndrome." (PMID 33224145, 2020).